BACE1 (beta-secretase 1)
Diseases named in the same sentence as BACE1 in open-access papers (continued):
Sharing a sentence is not in itself a finding about the gene and the disease.
Stroke (13 papers, 2007 to 2023). Sudden impairment of blood flow to a part of the brain due to occlusion or rupture of an artery to the brain. "While the mechanism of BACE1 elevation in AD and APP Tg brains is not fully understood, recent data indicate that BACE1 levels are upregulated during stresses associated with AD risk such as energy deprivation, hypoxia and stroke, oxidative stress and traumatic brain injury." (PMID 24992504, 2014). "We next investigated whether S-nitrosylation of BACE1 occurred in vivo in neurodegenerative disorders associated with high levels of nitrosative stress, such as stroke and AD." (PMID 21371311, 2011). "Based on these findings, we propose that the chronic sequelae of stroke may be ratcheting-up a myelin repair pathway, and that the consequent increase in BACE1 could be causing an inadvertent cleavage of its alternative substrate, AβPP, resulting in greater Aβ seeding and pathogenesis." (PMID 30249297, 2018). "While the mechanism of BACE1 elevation in brains of AD patients or mouse models of AD is not yet clear, recent data indicate that BACE1 levels are upregulated during stresses associated with AD risk, such as energy deprivation, hypoxia and stroke, oxidative stress, and traumatic brain injury." (PMID 26993139, 2016). "Using single cell and nucleus RNA sequencing data, we identified 15 BACE1 substrates which were specifically altered in human AD brain samples, when compared against other neurological diseases; stroke, TBI, EAE, and epilepsy." (PMID 35562959, 2022). "We have previously shown that BACE1 increases following caspase activation both in cellular models of apoptosis and in rodent models of stroke and TBI and proposed that caspase-mediated depletion of GGA3 is the underlying mechanism of BACE1 elevation." (PMID 29391027, 2018). "In an experimental stroke model used to study the effects of transient cerebral ischemia, ischemia led to an elevation in BACE1 protein and activity, and BACE1 immunoreactivity was strongly associated with TUNEL staining, a marker of apoptosis." (PMID 18005427, 2007). "To explore the mechanisms by which BACE-1 inhibits the beneficial phenotype of microglia, we noted that STAT3 was closely associated with the microglial polarization shift and microglia-dependent regulation of neuroinflammation and phagocytosis in stroke." (PMID 37552127, 2023). "With regard to a potential mechanism, in both models, we found that the stroke-induced Aβ and tau deposits co-localized with increased levels of β-secretase 1 (BACE1), along with its substrate, neuregulin 1 (NGR1) type III, both of which are proteins integral for myelin repair." (PMID 30249297, 2018). "Moreover, we have determined that GGA3 is depleted while BACE1 levels increase following experimental stroke and traumatic brain injury (TBI)." (PMID 27192432, 2016). "In summary, besides the application in the patients with cerebral ischemic stroke, we have identified anti-stroke herbal medicine TLJN as a modulator of BACE1 and γ-secretase complex, which provides a mechanistic clue for the application in neurodegenerative diseases such as AD." (PMID 23472157, 2013).
Hypertension (11 papers, 2018 to 2025). The presence of chronic increased pressure in the systemic arterial system. "Similarly, hypertension leads to a 45% decrease of CBF in selected brain regions, and the resulting upregulation of BACE1 may contribute to Aβ accumulation and the increased likelihood of suffering from AD that is associated with hypertension." (PMID 32865691, 2020).
Parkinson disease (10 papers, 2013 to 2025). A progressive degenerative disorder of the central nervous system characterized by loss of dopamine producing neurons in the substantia nigra and the presence of Lewy bodies in the substantia nigra and locus coeruleus. "Moreover, fungal meroterpenoids, hybrid polyketide-terpenoid metabolites, exhibit anti-cholinesterase and BACE1-inhibitory activity, offering promising leads for Alzheimer’s and Parkinson’s disease therapy." (PMID 41488566, 2025).
type 2 diabetes (10 papers, 2015 to 2025). "Insulin signaling plays an important role in the development of type 2 diabetes, and the insulin receptor has been indicated as a substrate of BACE1." (PMID 40507910, 2025). "Another group suggested that type 2 diabetes exacerbates the generation of A-beta via activation of BACE1." (PMID 27656136, 2016). "Type 2 diabetes-induced neurodegeneration in rats revealed a significant upregulation of gene expression of APP and BACE-1 when compared with control rats (p < 0.01)." (PMID 34834352, 2021).
Anxiety (9 papers, 2007 to 2025). Intense feelings of nervousness, tension, or panic often arise in response to interpersonal stresses. "Mice with BACE1 deficiency exhibit anxiety behaviors as well as impaired learning and memory, as assessed in the Y-maze, open field and Morris water maze, and in line with prior observations." (PMID 34158621, 2021). "RA-PR058 demonstrates potential as a multi-target AD therapeutic by reducing BACE1 expression, tau hyperphosphorylation, and anxiety-like behavior, coupled with favorable pharmacokinetics." (PMID 39931645, 2025). "Mice treated either BACE1 inhibitor consistently displayed impairment in cognitive functions including learning behaviors and anxiety in two different age groups." (PMID 34158621, 2021). "Our results showed a positive correlation between ADAM19 and psychosis (r = 0.595 p = 0.019); PS1 and mania (r = 0.535, p = 0.040); PS1 and depression (r = 0.567, p = 0.027) in BA9, and BACE1 with anxiety (r = 0.608, p = 0.03) in the hippocampus." (PMID 22590542, 2012). "BACE1-/- mice spent more time in central parts of the open-field and visited open-arms in the plus-maze test more often than wild type controls, indicating that BACE1 may play some role in anxiety." (PMID 18005427, 2007). "By giving BACE1-null mice the PAM for 45–60 days, we showed that chronic activation of mGluR1 significantly improved anxiety behaviors as well as learning and memory in BACE1-null mice, consistent with the improvements in LTP measures, indicating the beneficial effect of PAM." (PMID 34158621, 2021). "Thus, it possible that increased BACE1-mediated processing of NRG1 could lead to increased GABAergic transmission and reduced anxiety." (PMID 27192432, 2016).
Down syndrome (9 papers, 2013 to 2025). "In further support of these findings, we found that elevation of APP was associated with a decreased BACE1-mediated processing of CHL1 in human brains from subjects affected by Down syndrome." (PMID 29391027, 2018). "Moreover, elevation of APP was associated with a decreased BACE1-mediated processing of CHL1 not only in 12 months old 5XFAD mice but also in human brains from subjects affected by Down syndrome, most likely due to substrate competition." (PMID 29391027, 2018). "Furthermore, our findings suggest that BACE1 inhibition could exacerbate mechanism-based side effects in conditions associated with APP elevation (e.g. Down syndrome) owing to impairment of BACE1-mediated processing of CHL1." (PMID 29391027, 2018). "Consistent with this evidence, genetic reduction in BACE1 activity in a mouse model of Down syndrome improved endosomal volume and improved cholinergic markers without lowering Aβ levels." (PMID 30572184, 2019). "In order to further support our finding that increased levels of APP are associated with decreased BACE1-mediated processing of CHL1, we analyzed hippocampal tissue from subjects affected by Down Syndrome (DS) carrying an extra copy of chromosome 21." (PMID 29391027, 2018). "To test our previous hypothesis that PrPC may function normally to protect against AD by reducing BACE1 activity, we have explored the relationship between PrPC level and AD pathology in two contexts: first in sporadic AD, and second in Down's syndrome." (PMID 23577068, 2013). "However, BACE-1 inhibition might lead to APP (substrates of BACE-1) elevation and impair BACE1-mediated processing of endogenous CHL1 (cell adhesion molecule L1-like protein), exacerbating mechanism-based side effects in, e.g., Down syndrome associated with APP elevation." (PMID 38212785, 2024). "The observation of Aβ11pE-42 and Aβ11-42 in early, diffuse plaques in both AD but also early Downs syndrome and CUAP does not support a plaque-onset related role for BACE1 overactivation beyond a mechanism to combat an initial rise in Aβ levels." (PMID 40274785, 2025).
epilepsy (9 papers, 2010 to 2025). A brain disorder characterized by episodes of abnormally increased neuronal discharge resulting in transient episodes of sensory or motor neurological dysfunction, or psychic dysfunction. "There is also evidence of an association between BACE1 gene polymorphisms and focal seizures, particularly in males, indicating a potential genetic risk factor for epilepsy." (PMID 40291844, 2025). "Dysregulation of the BACE1/BACE1‐AS axis also has been implicated in both cardiac dysfunction and epilepsy." (PMID 35119166, 2022). "The previously reported regulation of VGSCs by BACE1 is an interesting candidate for an underlying mechanism of this phenotype, since mutations in both α and β-subunits have been linked to epilepsy." (PMID 20731874, 2010). "An interesting finding of the present study is that, consistent with previous research, epileptic AD mice exhibit considerable BACE1 signaling in the hippocampus, suggesting that chronic epilepsy induces BACE1 upregulation." (PMID 39545066, 2024). "There was a significant correlation between the expression level of BACE1 and its natural antisense (BACE1-AS) in the blood of patients with epilepsy." (PMID 36438002, 2022). "In the 9-month old epileptic 3×Tg-AD mice (3 months after epilepsy induction), the distribution pattern of BACE1 was altered in both the hippocampal formation and other temporal cortical structures." (PMID 23155407, 2012). "The results suggest that BACE1 (and APP) elevation, as well p-tau overexpression, could be potentially linked to aberrant synaptic/axonal plasticity in experimental epilepsy." (PMID 23155407, 2012). "The anatomical basis for epilepsy in the BACE1-/- mice is unclear." (PMID 20731874, 2010). "On the other hand, BACE1 deficiency may cause epilepsy through a none-enzymatic mechanism, as BACE1 interacts with an M-current-producing KCNQ (Kv7) family member, resembling the function of a β-subunit." (PMID 28469554, 2017). "We identified a known anti-epilepsy hydantoin drug, phenytoin, as a screening hit in the MBP-APPC125 BACE1 cleavage screening assay." (PMID 40399225, 2025). "In contrast to controls, in both 11- (3 months after epilepsy induction; images not shown) and 14-month (6 months after epilepsy induction) old epileptic 3×Tg-AD mice, BACE1 IR was clearly present in the inner molecular layer of the dentate gyrus." (PMID 23155407, 2012).
ischemia (9 papers, 2007 to 2023). A hypoperfusion of the BLOOD through an organ or tissue caused by a PATHOLOGIC CONSTRICTION or obstruction of its BLOOD VESSELS, or an absence of BLOOD CIRCULATION. "In the CA3 region of the hippocampus, the expression of the β-secretase gene (BACE1) after ischemia with 2- and 7-day survival was lower than the control values, but on day 30, it was higher than the control values." (PMID 31713815, 2020). "BACE1 levels are also increased in some injury conditions including brain trauma and ischemia, suggesting a possible role of BACE1 as a stress-response protein." (PMID 21182789, 2010). "The observations that BACE1 levels are also elevated following brain trauma and ischemia add further support for the role of BACE1 as a stress response protein." (PMID 18005427, 2007). "In addition, the current findings confirm the upregulation of BACE1 and SCD1 associated with astrogliosis by ischemia in the rat hippocampus." (PMID 37744400, 2023). "Results indicate that there is a disagreement between the expression of the BACE1 gene and the APP, whose expression has been decreased below the control values in the ischemic CA1 region and temporal cortex two days post-ischemia." (PMID 35741821, 2022). "In the rat model of ischemia, this reduction in GGA3 levels was co-ordinated with caspase activation and increased BACE1 protein levels." (PMID 18005427, 2007).
Senile plaques (9 papers, 2012 to 2023). Senile plaques are extracellular deposits of amyloid in the gray matter of the brain. "Attention has shed light on the beta-secretase 1 (BACE-1) inhibitors because BACE-1 is an enzyme involved in the formation of amyloid or senile plaques, a hallmark of AD." (PMID 32503261, 2020). "Increased BACE1 expression, concentration, and activity in and around senile plaques have been reported in several studies in cognitively healthy elderly individuals and patients with AD." (PMID 22272179, 2012). "In addition, ECH significantly reduced the deposition of senile plaques in the brain and decreased the expression of BACE1 in APP/PS1 mice through activating PI3K/AKT/Nrf2/PPARγ pathway." (PMID 35665898, 2022). "Compounds of this type have been developed as potential AD therapeutics due to the role of BACE1 in APP cleavage and generation of the Aβ peptides found in senile plaques." (PMID 37269953, 2023). "BIN1 directly interacts with RIN3 to initiate RAB5-mediated endocytosis, which is essential for β-secretase (BACE1)-mediated β-secretase cleavage of β-amyloid precursor protein (APP) to generate Amyloid-β (Aβ), the key component of senile plaques in AD." (PMID 35241726, 2022).
glioblastoma (8 papers, 2012 to 2025). The most malignant astrocytic tumor (WHO grade IV). "BACE1 is also proposed as a drug target for glioblastoma, where it was recently described to control macrophage phagocytosis of tumor cells." (PMID 36810097, 2023). "Inhibition of BACE1 suppressed glioblastoma growth by stimulating macrophage phagocytosis of glioblastoma stem cells." (PMID 36810097, 2023). "MiR-339-5p reduced in AD patients brains; miR-339-5p can target BACE1 and inhibited BACE1 protein expression in human glioblastoma and primary brain cultures." (PMID 30881384, 2019). "MiR-339-p reduced in AD patients brains; miR-339-5p can target BACE1 and inhibited BACE1 protein expression in human glioblastoma and primary brain cultures." (PMID 30881384, 2019). "For example, miR-124 alleviates cell death in the process of AD by targeting BACE1, while increases cell death in glioblastoma by regulating TEAD1, MAPK14/p38α, and SERP1." (PMID 26041995, 2015). "Furthermore, BACE1 reduced the phagocytosis of tumor cells in glioblastoma by activating the tumor-promoting macrophages via cleaving interleukin-6 receptor (IL-6R) and activating IL6/sIL-6R/STAT3 signaling." (PMID 38201438, 2023). "Furthermore, we recently identified BACE1 was important for maintaining a tumor-promoting macrophage phenotype in glioblastoma, suggesting it might have a multi-faceted role in the progression of solid cancers in the brain." (PMID 40601773, 2025). "Besides neuronal IL-6 signaling, BACE1 may also control IL-6 signaling in tumor-promoting macrophages in glioblastoma." (PMID 36810097, 2023). "Förster resonance energy transfer (FRET) -based techniques have recently been applied to study the interactions between β-site APP-cleaving enzyme-GFP (BACE1-GFP) and amyloid precursor protein-mRFP (APP-mRFP) in U373 glioblastoma cells." (PMID 23443094, 2012). "This phenotype required BACE1 cleavage of IL-6R, which is expressed in macrophages, but not neurons, making BACE1 a potential drug target for glioblastoma." (PMID 36810097, 2023).
Hyperglycemia (8 papers, 2013 to 2022). An increased concentration of glucose in the blood. "Hyperglycemia is known to cause elevated oxidative stress and both BACE1 and presenilin 1 expression are known to be stimulated by oxidative stress accompanied by an increase in Aβ production." (PMID 23894546, 2013). "Hyperglycemia and hyperlipidemia increase BACE1 activity and Aβ peptide levels in tissues and plasma, linking key metabolic disease markers with increased amyloid processing." (PMID 32407295, 2020). "Hyperglycemia increased BACE1 expression, which was significantly reduced by AM404 administration (P < 0.05)." (PMID 30426182, 2019). "Furthermore, increased β-site amyloid precursor protein–cleaving (APP-cleaving) enzyme 1 (BACE1), APP, and β-amyloid (Aβ) are linked with vascular disease development and increased BACE1 and Aβ accompany hyperglycemia and hyperlipidemia." (PMID 32407295, 2020). "In this study, hyperglycemia increased BACE1 expression, Aβ deposition, tau protein phosphorylation, gliosis, and peripheral inflammation and decreased the levels of activated Akt and pS9-GSK3β (the inactive form of GSK3β) in 3×Tg-AD mice, whereas the AM404 treatment reversed these changes." (PMID 30426182, 2019). "This study evaluated the neuroprotective effects of piperine and expression of five candidate genes (BACE1, PSEN1, APAF1, CASPASE3, and CATALASE) in rat’s cerebral cortex induced hyperglycemia with STZ rat model." (PMID 33737876, 2020). "Furthermore, it has been reported that BACE1 is located in the lipid raft, and a change in lipid raft cholesterol could affect BACE1 activity and result in changes to Aβ production, suggested that lipid raft modification by hyperglycemia may be a potential trigger of AD pathogenesis." (PMID 27829662, 2016). "Our findings are consistent with those presented as an abstract by researchers at Novartis; the potent non-selective BACE1/BACE2 inhibitor, SMI NB-360, did not improve hyperglycemia, glucose tolerance or increase beta-cell mass after chronic treatment in diabetic ob/ob mice." (PMID 26840340, 2016).
depression (7 papers, 2012 to 2024). "In addition, high BACE1 level is also detected in the peripheral blood of patients with depression." (PMID 37284450, 2023). "The inhibition of BACE1, AChE, and BChE, in AD, hMAO-B in PD, and MAO-A in depression was performed efficiently by SPs, glycoproteins, carotenoids, especially fucoxanthin, and phlorotannins." (PMID 35736165, 2022). "Notably, the depression groups LLD AD and LLD NoAD showed significant differences in Ng, BACE1 and Ng/BACE1 ratio with higher levels for Ng (pADJ < 0.001), BACE1 (pADJ < 0.05) and the Ng/BACE1 ratio (pADJ < 0.01) in the LLD AD group." (PMID 34645914, 2021). "Given the established neurobiological overlap among depression, MCI, and AD, the NGR/BACE1 ratio may represent a suitable clinical tool for the AD diagnostic workup." (PMID 33066807, 2020). "Further prospective longitudinal studies are needed to understand the role of the NGR/BACE1 ratio as a biomarker to improve the classification between non-neurodegenerative forms of MCI, including but not exclusively depression, and early AD." (PMID 33066807, 2020).